NF1 (neurofibromin 1)
Diseases named in the same sentence as NF1 in open-access papers (continued):
Sharing a sentence is not in itself a finding about the gene and the disease.
cancer (continued). "Hence, there is a growing hypothesis that tamoxifen might be less effective in cancers involving NF1 mutations; however, clinical evidence is missing." (PMID 25889501, 2015). "For instance, nine of our candidate cancer genes were also contained in the Cancer Gene Census list, which comprises 487 genes causally linked to cancer, representing a highly significant enrichment (Abl2, Braf, Fbxw7, Foxp1, Ipo11, Mllt3, Fas, Pten, and Nf1; p<0.0002, Fisher’s exact test)." (PMID 23940809, 2013). "In one small-scale in vitro screen, 21 clinically relevant cancer drugs were tested alone or in combination with MEK or PI3K inhibitors in both 2D and 3D cultures of NF1-deficient HGG cells." (PMID 41294711, 2025). "In metastatic HER2-positive cancer resistant to anti-HER2 therapies, somatic mutations often activate ERK/MEK signaling through the loss of NF1, the GTPase-activating protein that deactivates RAS." (PMID 40080721, 2025). "They found that the proportion of NF1 mutations increased with the progression of the MPNST and that the tumors became much more copy-number aberrant as they progressed to cancer." (PMID 39857962, 2025). "The UK adopts moderate cancer risk guidelines of NICE, advising women with NF1 to attend breast screening from 40 years." (PMID 38859614, 2025). "To address these issues, we are currently testing MSU-42011 in additional NF1 models (e.g., transgenic mice) to evaluate its interactions with specific pathways, immune cells, and cancer progression, providing insights into its mechanisms of action." (PMID 40563570, 2025). "Other “Tier 1” cancer-related gene mutations in the COSMIC Cancer Gene Census21 present in the 15 most frequently mutated genes include PIK3R1 (4%), NF1 (4%), NOTCH1 (4%), APC (3%), and ATR (3%)." (PMID 40057511, 2025). "Nevertheless, it is clear that direct Ras inhibition in some capacity will likely prove beneficial in NF1 mutant tumors and other cancers driven by inappropriate activation of wildtype Ras proteins." (PMID 40587782, 2025). "Patients with NF1 have a cancer incidence that is five to ten times greater than in the general population, with 40% of patients developing cancer by the sixth decade of their life." (PMID 40649916, 2025). "Approximately 1/3000 individuals are born with NF1, and the population is nearly 10 times more likely to develop cancer than the general population." (PMID 40585258, 2025). "Overall, a germline pathogenic variant (gPV) in a cancer predisposing gene was identified in 9.7% of individuals (CHEK2, FANCM, NF1, POT1 and PTEN) and a candidate variant in 4.2% of individuals (HOXB13, MAX and RECQL4)." (PMID 39979679, 2025). "For cell cycle regulation and cancer, the genes CCND1 and E2F7 (cell cycle regulation) and BRCA2, NF2, BRCA1, and NF1 (cancer) were found to be upregulated relative to humans." (PMID 40149424, 2025). "Self- and parent-proxy reports of HRQoL of children with NF1 + CI were significantly poorer than children with cancer for psychosocial health and school functioning and also for parent-proxy reports of social functioning." (PMID 40471421, 2025). "This likely contributed to the relatively limited studies of NF1-mutant cancers compared with other oncogenic drivers." (PMID 41170454, 2025). "Children with NF1 + CI had significantly better HRQoL for Physical Health self- and parent-proxy reports when compared to children with cancer." (PMID 40471421, 2025). "Trametinib, a mitogen-activated protein kinase (MEK) inhibitor targeting MEK1 and MEK2, crucial components of the MAPK/ERK pathway, has emerged as a potential treatment of NF1 altered cancers." (PMID 41170454, 2025).
cancer (continued). "Notable exceptions were NF1, KRAS, and BRAF alterations in basal-type cancer, as well as increased NF1 and KRAS in HER2-positive disease." (PMID 40080721, 2025). "In this regard, the proposed use of lamotrigine for NF1-OPG therapy underscores the value of interfering with neuron-cancer interdependence." (PMID 41497446, 2025). "Three other genes were found to be significant prognostic factors for overall survival in more than one cancer type; NF1, PIK3CA and PTEN." (PMID 39277826, 2024). "As a MEK inhibitor, selumetinib can induce cancer cell apoptosis, which is the core mechanism of its treatment of NF1." (PMID 39193326, 2024). "The effect of NF1 on the number of days of unemployment remained essentially unchanged after adjustment also for the history of cancer within the past three years." (PMID 37460655, 2024). "Ten tumors were negative for mutations in KIT, PDGFRA, and RAS-pathway genes (BRAF, RAS isoforms, and NF1), and for all other 161 cancer-relevant genes that were included in our NGS panel." (PMID 39199677, 2024). "Although TCGA and GTEx database analysis revealed a significant correlation between NF1 and YAP1 in a variety of digestive tract-related malignancies, the role of NF1 in promoting or suppressing cancer in other solid tumors remains undetermined." (PMID 37147639, 2023). "The first group of genes was well-known cancer-related genes, i.e., Fgfr2, Hras, Tgfbr2, Nf1, and Erbb2." (PMID 37063417, 2023). "The clinical relevance of NF1 is highlighted by its ability to trigger the development of both benign and malignant tumors, typically in the nervous system; hence, NF1 ought to be detected early in children to identify said malignancies and promote health." (PMID 37181996, 2023). "The selected pG4-BS include sequences from various gene segments of cancer-associated genes, such as EZR, PRN1, RARA and NF1." (PMID 37094040, 2023). "MEK inhibitors have been employed in several types of human cancers and their use has been recently proposed in the treatment of NF1-related tumors." (PMID 36923276, 2023). "Considering the signaling cascade involved in NF1-related cancers, interestingly, Ras activation is known to enhance ROS production in normal and neoplastic cells." (PMID 37627552, 2023). "The newly identified genes included several well-known cancer drivers, such as Fgfr2, Hras, Tgfbr2, Nf1, and Erbb2, as well as others whose function in cancer remains elusive." (PMID 37063417, 2023). "The sensitivity of our NF1-HGG lines to a range of anti-cancer compounds, inhibiting different targets, was evaluated alone and in combination with MEK and PI3K inhibitors." (PMID 36730269, 2023). "The development of benign and malignant tumors is characterized by NF1, with the largest chance of developing symptomatic visceral tumors occurring within the first six years of life." (PMID 37773168, 2023). "Based on epidemiologic studies, cancer incidence in NF1 is approximately four-fold higher than in general population." (PMID 35885913, 2022).
cancer (continued). "As a highly heterogenous cancer, CM harbours various genetic alteration including BRAF mutation, RAS mutation, NF1 mutations, etc., which plays an critical role in the biological behavior of CM and is closely related to the prognosis of CM patient." (PMID 35751033, 2022). "Mutations in genes encoding proteins such as PTEN, TSC1/2, serine threonine kinase 11 (LKB1) and NF1 that lie upstream of the mTOR complexes generate cancer syndromes." (PMID 35001007, 2022). "We envision that enhancement of SIRT3 activity and replenishment of NAD+ levels result in a multifaceted metabolic rewiring, which can oppose NF1-related cancer growth by affecting multiple bioenergetic pathways." (PMID 35393510, 2022). "Among these, the genes involved in PI3K-Akt-mTOR signaling axis, such as PTEN, NF1 (neurofibromin 1), TSC1(TSC complex subunit 1), TSC2 (TSC complex subunit 2), were associated with inherited risk for both cancer and ASD." (PMID 36339838, 2022). "According to previous studies, genetic alterations including loss of NF1, EED, and SUZ12, have been demonstrated to activate the RAS/MAPK pathway in various human cancers including MPNSTs." (PMID 35875109, 2022). "Other cancers more commonly encountered in patients with NF1 include the malignant triton tumors (MTTs), which are a rare variant of MPNSTs." (PMID 35053664, 2022). "Here, we report a case of multiple primary malignant tumors (NF-1, GIST, SBA and Gangliocytomain), and investigate the possible relationship between them." (PMID 36620543, 2022). "In cancer, the inhibition of NF1 contributes to the generation of melanomagenesis by enhancing the activation of PI3K signaling, this inhibition favours angiogenesis, escaping apoptosis, migration, and cancer cell invasion." (PMID 34446793, 2021). "The main genetic drivers of these chronic sun-damaged cancers are B-raf proto-oncogene (BRAF), neurofibromin-1 (NF-1), and NRAS mutations." (PMID 34155457, 2021). "Meanwhile, the amplification peaks of cancer suppressors containing NF1 and MAP2K4 were detected in patients with high level of PPP2R2B expression." (PMID 33407498, 2021). "Regarding specific cancer-associated genes, the CYT-high subgroup had more CNAs, including gains in NF1, CDK12, ERBB2, RARA, MDM4 and MYC; and losses in BRCA1, CD274 and APC." (PMID 34316699, 2021). "Moreover, somatic NF1 mutations may be critical drivers in multiple cancers." (PMID 34638749, 2021). "Neurofibromatosis type 1 (NF-1) is a tumor suppressor gene that inhibits RAS-GTP activation, and it has recently been reported that NF-1 mutations are associated with cancer." (PMID 33952249, 2021). "This cohort study was conducted among patients with NF1 at a single academic cancer center from 1985 to 2020 with median (range) follow-up of 2.9 years (36 days to 30.5 years)." (PMID 33734413, 2021). "The subjects with the disorder have an increased susceptibility to the development of benign and malignant tumours, because RAS is overactivated as a result of the NF1 loss-of-function mutation." (PMID 34449562, 2021). "In contrast to dominant mutations of EGFR, NF1, RAS, and RAF, there are some rare activating mutations of Sos, MEK, and ERK in cancer genomes that constitutively turn on RAS/RAF/MEK/ERK signaling." (PMID 35582307, 2021). "We found a rather narrow range of other genes (KMT2D, FBXW7, GNAS, ARID1A, NF1 and CTNNB1) harbouring mutations in 6–12% of the patients and a long tail of cancer genes with mutations in <6%." (PMID 34647903, 2021).
cancer (continued). "Crucially, LV-miniMg-∆MEF3/NF1-HSV differentially affected human cancer cells and myoblasts, with reduced proliferation in the RH30 and RH41 ARMS cell lines." (PMID 32973362, 2021). "Related to this observation, malignant tumors were significantly over-represented in the NF1-deleted group (p value = 0.0072 after correction for multiple testing)." (PMID 34199217, 2021). "Targeting microenvironments has been used for cancer treatment, and it is a promising approach for the treatment of NF1-related tumors." (PMID 34359780, 2021). "Secondary outcome measurement is enrichment of RAS regulatory gene (NF1, PTPN11, and CBL) in BRAF variant cancers." (PMID 33507258, 2021). "SMAD4 and NF1, the known cancer-related genes in the CGC database, are the common ceRNAs of NEAT1 in all six CCNs." (PMID 33987091, 2021). "Genes such as EGFR, PIK3CA, DROSHA, MDM4, and APC were located inside recurrently aberrant regions, while other known cancer-genes such as NF1, MET and mTOR were identified as cis-genes and located outside the most recurrently altered regions." (PMID 34625038, 2021). "For women with a PALB2, CDH1 or NF1 mutations, the NCCN recommends an annual mammogram and annual MRI beginning at age 30, unless the age of cancer diagnosis within the family was earlier." (PMID 34573353, 2021). "For patients with NF1, which is a hereditary and systemic disease with a high incidence of malignant tumors, it would be a great relief to increase the number of such clinics in Japan and the rest of Asia." (PMID 34099792, 2021). "Several cancer-associated genes have been identified on chromosome 17q, including PPM1D, EME1, BRCA1, ERBB2, NF1, RAD51C, BRIP1 and BIRC5." (PMID 34885154, 2021). "The reported individuals have high prevalence of severe NF1 phenotype, including plexiform and/or spinal neurofibromas, symptomatic OPGs, skeletal abnormalities, and other malignant neoplasms." (PMID 31906320, 2020). "This role has been reinforced by recent large pan-cancer genomic sequencing studies which revealed the presence of NF1 alterations in 6% of patients’ tumors." (PMID 31979111, 2020). "NF1-specific malignancies, including MPNSTs, typically manifest early in life and are responsible for the relative excess in cancer incidence and mortality observed in children and young adults." (PMID 32650362, 2020). "The RAS GAP Neurofibromin (NF1) is known to play an important role in maintaining low levels of RAS-GTP in unstimulated cells, with loss-of-function NF1 mutations being common in cancer." (PMID 33153459, 2020). "The role of microRNAs in cancer progression was examined in NF1-derived MPNST cell lines by transiently modulating microRNA levels." (PMID 32076030, 2020). "In gastric cancer, the upregulation of miR-107 and miR-130b-5p was shown to promote proliferation, migration, and invasion of cancer cells, partially via reduction of their respective targets NF1 and RASAL1." (PMID 33096593, 2020). "This upregulation requires ERK activity and inhibition of p38 and was also observed in other cancer cells carrying KRAS, BRAF, or NF1 mutations, suggesting that p38 antagonizes this resistance pathway in several different cancer types." (PMID 32046099, 2020). "Therefore, NF1 mutations might be novel therapeutic targets for cancer treatment." (PMID 33061844, 2020). "Specifically, poorer survival was associated with samples that had a SPRED1 aberration in combination with another cancer driver mutation: NRAS, NF1 or KIT (log-rank test, p = 0.0074)." (PMID 33067454, 2020). "NF-1 is considered to be a syndrome that increases disposition to tumors, since individuals with NF-1 are 10 to 50 times more prone to a diverse spectrum of benign and malignant tumors than the general population." (PMID 33308182, 2020).
cancer (continued). "This regulation suggests a relationship between Cry1/2 and Bmal1 and Prkaa2, Ccnd1and Nf1 in promoting CJL mediated cancer." (PMID 31523185, 2019). "Two patients (P20 and P21) had variants in NF1, a negative regulator of RAS, inactivated by mutation in various cancers." (PMID 31226844, 2019). "Various cancer types have been shown to carry druggable targets for mTOR inhibitors, including mutations in MTOR, TSC1, TSC2, NF1, PI3KCA, PIK3CG, STK11, and RHEB." (PMID 31443247, 2019). "In the era of precision medicine, when dealing with a cancer-prone syndrome like NF1, new technologies, such as ncRNA-based liquid biopsies, cannot be ignored, and should be developed for screening and early detection of malignant complications." (PMID 31694342, 2019). "The second patient was first seen at our cancer genetics clinic at the age of 42 with clinical diagnosis of NF1." (PMID 31507634, 2019). "PGL/PCC development has been related to mutations in three genes that cause well-known cancer susceptibility syndromes: VHL (von hippel-lindau tumor supressor), NF1 (neurofibromin 1), and RET (ret proto-oncogene)." (PMID 31365623, 2019). "Altogether, these results illustrate the antagonistic role of the Nf1+/− microenvironment regarding cancer progression, in which it fosters de novo benign tumorigenesis but impairs malignant transformation." (PMID 30479396, 2018). "The initial report of an association between MLH1 and splicing mutations also associated other cancer related genes such as BRCA1, BRCA2, and NF1 with disrupted splicing." (PMID 29505604, 2018). "Individuals with germline inactivation of the NF1 gene have a propensity to develop both benign and malignant tumours." (PMID 30174724, 2018). "A second set consisted of an additional 15 cancer-related genes (Nf1, Mki67, Mllt4, Fgfr2, Ctnnb1, Fat1, Clp1, Fat4, Arid1a, Nat1, Nat2, Setd2, Impg1, Nbas and Npat)." (PMID 29925311, 2018). "Nevertheless, we were able to validate expressed mutations in two previously reported cancer drivers: DICER1 and NF1." (PMID 29459759, 2018). "Performance was comparable to that of NF1 classifiers built using cancer-type-specific and pan-cancer models." (PMID 29617658, 2018). "In summary, our current study showed that DAW22 inhibited both sporadic and NF1‐related MPNST cancer cell proliferation and induced apoptosis by targeting AKT, ERK, and CTNNB1 pathways." (PMID 30112810, 2018). "NF1 amplification, and presumably increased neurofibromin expression and hence activity, has been identified in many cancers, including breast (17%), pancreatic (21.5%), uterine endometrial (1.8%) and neuroendocrine prostate cancer (21.5%)." (PMID 28637487, 2017). "Many studies have demonstrated that NF1 plays an important role in many cancers such as brain tumors, breast cancer, sporadic colon cancer, lung cancer, pheochromocytomas and ovarian tumors." (PMID 29137312, 2017). "Alterations in the tumor suppressor gene neurofibromin (NF1) enhance expression of the Ras signaling pathway, which is involved in the evolution of many cancers." (PMID 28542306, 2017). "Several known cancer mutations were seen in unique samples (KRAS p.G12D, BRAF p.D594G, NF1 p.R1362*, and ZFAND1 p.R130*)." (PMID 28852190, 2017).